AFP (alpha fetoprotein)
Diseases named in the same sentence as AFP in open-access papers (continued):
Sharing a sentence is not in itself a finding about the gene and the disease.
tumor (continued). "Additionally, hsa-miR-210 expression was positively correlated with AFP, pathological grade, TNM stage, tumor stage and vascular invasion, suggesting that hsa-miR-210 indicate the extent of HCC malignancy." (PMID 30560088, 2018). "Serum tumor marker levels were 8.8 ng/ml in carcinoembryonic antigen (CEA) and 28.3 ng/ml in AFP." (PMID 30191347, 2018). "All other routine tests and tumor markers (CEA, CA125, CA15.3, CA 19–9, AFP) were normal." (PMID 29301491, 2018). "The tumor cells were diffusely positive for AFP, CK, CK8/18, GPC-3, and hepatocyte, but negative for CD30, CD34, CK19, D2–40, PLAP, and vimentin." (PMID 29351804, 2018). "In CRC, AFP and CEA have been used as reliable tumor markers for monitoring tumor progression." (PMID 29849497, 2018). "Tumor characteristics favoring malignancy include size ≥8 cm, presence of thick septations >2–3 mm and nonhyperechoic solid nodular or papillary components, and tumor markers (LDH, AFP, β-HCG, and CA-125)." (PMID 30486309, 2018). "They induced a significant increase in liver relative weight and serum levels of cancer markers (AFP and GGT) and liver enzymes (ALT, AST, and ALP), as well as intensive immunostaining for the HCC marker GST-P, and increased number and area of tumor AHF as compared to HCC rats injected by PBS." (PMID 30224923, 2018). "Circulating tumor markers (β-subunit of human chorionic gonadotropin (β-HCG), alpha-Fetoprotein (AFP), and Lactate Dehydrogenase (LDH)) are frequently used for monitoring disease recurrence in TGCT patients, though they lack diagnostic sensitivity and specificity." (PMID 30321995, 2018). "In addition to measuring the ctDNA concentration for each patient, we also measured the concentration of several known tumor biomarkers such as CEA, AFP, CA19-9, CA125, and CA72-4." (PMID 29914973, 2018). "Nevertheless, the PD-L1 expression has no obvious connection with age, sex, AFP, tumor size, number of tumors, vascular invasion, HBVs-Ag, Anti-HCV, differentiation or TNM stage." (PMID 30254644, 2018). "The absence of AFP from the tumour environment has been shown to greatly reduce tumour lethality and HCC growth, whereas the presence of AFP increases tumour lethality." (PMID 30301886, 2018). "The tumor factors include the maximum tumor diameter (MTD), number of tumors, presence of macroscopic (clinically evident) portal vein thrombosis (PVT), and blood levels of alpha-fetoprotein (AFP)." (PMID 30009156, 2018). "Other prognostic variables included AFP levels, HCC tumor size, BCLC stage, and ART timing." (PMID 29467672, 2018). "Clinical evaluation and laboratory results were nonspecific, and serum tumor markers including carcinoembryonic antigen, cancer antigen (CA) 19-9, alpha-fetoprotein (AFP) and squamous cell carcinoma antigen were within their normal ranges." (PMID 30594949, 2018). "By the Cox regression model analysis, serum iron levels <15.1 μmol/l together with higher AFP levels, worse BCLC stages, and larger tumor size showed higher mortality of HBV-related HCC patients (hazard ratio = 2.280, 95% confidence interval, 1.815–2.865; P < 0.001)." (PMID 29467672, 2018). "AFP/AFPR brings about Ca2+ influx, so the intracellular Ca2+ increases, then the intracellular CAMP correspondingly rises, enhancing protease A activity, prompting DNA synthesis, and achieving the purpose of tumor cell proliferation." (PMID 29805966, 2018). "Chi-square and Kruskal-Wallis tests revealed significant intergroup differences in the HBs Ag status (positive/negative), presence/absence of portal vein invasion, size of the largest tumor nodule (≤3.0 cm/>3.0, cm), and the serum AFP level (ng/mL)." (PMID 30301934, 2018). "The survival benefit was more obvious in patients with elevated AFP, absence of metastasis, single tumor, enlarged tumor, and HBsAg positivity." (PMID 29435900, 2018). "As to tumour markers, in all cases, the LDH was high and, in the other two, HCG and AFP." (PMID 30792805, 2018).
tumor (continued). "The results presented here support the notion that the ramucirumab antitumour effect is not restricted to patients with AFP or objective tumour response but rather has some activity in all tumours with varying degree." (PMID 29808014, 2018). "It has been reported that serum AFP is a tumor marker that could be commonly used for diagnosis, predicting prognosis, and monitoring recurrence in HCC patients with high AFP level after resection [REMOVED HYPERLINK FIELD]." (PMID 30312171, 2018). "CSCs-exosomes induced a significant increase in liver relative weight and serum levels of cancer markers (AFP and GGT) and liver enzymes (ALT, AST, and ALP), intensive immunostaining for the HCC marker GST-P, and an increased number and area of tumor nodules as compared to HCC rats injected by PBS." (PMID 30224923, 2018). "In univariate analysis, sex, age, pre-existing disease, liver function, AFP, operative method, operative margins, tumor number, CLIP score were not significantly different between the surviving patients and those who died." (PMID 30180193, 2018). "However, the percent of patients with PVT was also found to significantly increase with increasing blood alpha-fetoprotein (AFP) levels and tumor multifocality." (PMID 30009156, 2018). "χ2 test showed that positive SKA1 expression was significantly correlated with higher serum AFP (P = 0.035), larger tumor size (P = 0.002) and late TNM stage (P = 0.009), but not with gender, age, differentiation or HBsAg." (PMID 30537941, 2018). "The AFP and HCG tumour markers were found in normal parameters and the LDH in 2480UI." (PMID 30792805, 2018). "However, predisposing factors include increased MTD, with increased levels of the HCC plasma tumor markers des-gamma carboxyprothrombin (DCP) and AFP, decreased serum albumin, and elevated platelet counts." (PMID 30009156, 2018). "As for tumor characteristics, low fibrosis group had more-higher frequency in large tumor size (greater than 2 cm), negative AFP value, and well or moderately differentiated pathological grade." (PMID 30445928, 2018). "Immunochemical staining with anti-AFP antibody was performed, and some hepatocytes around the tumor were stained, but the inside of the tumor did not stain at all." (PMID 30203247, 2018). "We observed nothing in this case that suggested the presence of HCC: no HCC components in the tumor; negative immunostaining for Hep-Par1, glypican-3, and AFP; no chronic liver diseases; and normal serum AFP levels." (PMID 29721707, 2018). "Both serum GPC3 and AFP levels were not affected significantly by age, sex, tumor size, PRETEXT stage and the status of lymphovascular invasion or metastasis." (PMID 28378832, 2017). "Among the tumor-related factors, a serum alpha-fetoprotein (AFP) level >20 ng/mL, multiple tumors, a tumor size >3 cm, the presence of vascular invasion, and non-curative treatments were also the independent risk factors associated with poor OS rates." (PMID 28209963, 2017). "Since AFP is an important clinical tumor marker for HCC growth and aggressiveness, we examined the effects of GSK1838705A and OSI-906 on Regorafenib/VK1-mediated inhibition of AFP secretion levels after 48 h, using the two AFP-secreting human HCC cell lines, PLC/PRF/5 and HepG2." (PMID 29262576, 2017). "A univariate analysis identified the following as significant contributing factors: age, Child-Pugh classification, MELD score, serum AFP level, ECOG-PS, tumor size, number of tumors, presence of vascular invasion, extrahepatic spread, and BCLC classification (all p<0.05)." (PMID 28954003, 2017). "Indeed, the single use of our 12 candidate markers showed modest predictive performance as well as AFP or PIVKA-II, which are currently used as tumor markers in HCC." (PMID 29050343, 2017).
tumor (continued). "The secretion of AFP by pHCC cells suggests that the Oncopig HCC model mimics AFP-producing HCC, with the advantage that AFP levels can be used to monitor tumor progression and treatment response in the Oncopig in drug trials for later application to human HCC." (PMID 28969016, 2017). "However, although AFP is poor for early HCC detection, serum AFP levels are efficient in predicting the disease outcome and monitoring tumor progression in AFP-producing HCC patients." (PMID 28031532, 2017). "Tumor markers at the time of diagnosis were assessed and elevated carcinoembryonic antigen (CEA), cancer antigen (CA) 19-9, CA125, CA15-3, and alpha fetoprotein (AFP) were recorded in 32 (30.2%), 26 (24.5%), 24 (22.6%), 6 (5.6%) and 3 (2.8%) patients, respectively." (PMID 28977975, 2017). "But the impact of AFP was still controversial, some studies also showed there was no prognostic value for the tumor less than 3 cm." (PMID 29290957, 2017). "However, conventional tumor markers, including human chorionic gonadotropin (HCG), alpha‐fetoprotein (AFP), and lactate dehydrogenase (LDH), are elevated in <60% of patients." (PMID 28317343, 2017). "We assumed that tumor response after TACE, baseline AFP value, and reduction of AFP level after TACE might be independent prognosis factors that impact the survival in patients who underwent HR after TACE." (PMID 27880724, 2017). "For example, since tumor biopsy was often not considered necessary in patients with high AFP levels, a subgroup analysis of patients with normal AFP levels with and without tumor biopsy was performed." (PMID 28154760, 2017). "Alpha-fetoprotein (AFP) and carcinoembryonic antigen (CEA) are clinically important tumor markers." (PMID 28475387, 2017). "The basic question addressed in this proof-of-concept study is whether embryonic miR levels can predict a relapse of (T)GCC better than the conventional tumor biomarkers B-HCG, AFP or LDH." (PMID 28612337, 2017). "Furthermore, the alpha fetoprotein (AFP), tumor size, pathological satellite, microvascular invasion, TNM stage and STAT3 levels were statistically correlated with DFS." (PMID 28032598, 2017). "In univariate analysis, alpha-fetoprotein (AFP) level, gamma-glutamyl transpeptidase (GGT) level, tumor size, tumor number, vascular invasion, tumor encapsulation, satellite lesion, BCLC stage, and HOXB7 expression were unfavorable predictors for OS and/or TTR (except tumor size)." (PMID 28454092, 2017). "PCT, AFP, GGT, tumor size and positive for HBVDNA were found to be independent risk factors of OS." (PMID 28700480, 2017). "No statistical differences were noticed in the tumor characteristics, such as diameter, number of tumors, AFP level, microvascular invasion (MiVI), and Edmonson grade, among the 4 groups." (PMID 28816936, 2017). "The lesions macroscopically recognized as tumors exhibited high AFP mRNA expression levels, suggesting that HCC was induced as expected by single DEN administration and macroscopic separation between the tumors and non-tumor tissues was appropriate." (PMID 28710407, 2017). "By univariate analysis, significant risk factors for the reduced survival of stage B patients included serum albumin level, AFP, PIVKA-II, AP-factor, anatomical resection, blood loss, tumor number, microscopic portal vein invasion, and a noncancerous liver." (PMID 28830473, 2017). "Analysis of other elevated tumor shed antigens (TSA) commonly monitored in other prominent cancer types including CA15-3, CA19-9, CEA and AFP (PSA was omitted due to gender specificity) on clinical response were conducted from the serum of 549 patients in the post hoc set." (PMID 28881712, 2017). "However, lab tests reflect the overall conditions of the body with the use of only a few markers for tumor screening, such as carcino-embryonic antigen, CEA and alpha fetoprotein, AFP." (PMID 29152097, 2017).
tumor (continued). "Significant correlations could be found between overall survival and dichotomously separated patient or disease characteristics, namely for ECOG status, CLIP score, preceding tumor surgery, CRP, AFP and LDH concentrations in serum at study inclusion." (PMID 29098441, 2017). "Moreover, FAK gene over-expression was significantly correlated with high serum levels of alpha-fetoprotein and large tumour size, thus suggesting FAK mRNA levels as a potential predictor of tumour recurrence and overall survival." (PMID 28067792, 2017). "The increase of AFP levels > 500 ng/ml is correlated with the tumor size: 80% of small HCC show no increase of AFP concentration." (PMID 28077782, 2017). "In our case we determined tumor markers β-HCG, LDH, and AFP to diminish doubts about malignancy." (PMID 28514960, 2017). "There was no obvious difference between native liver survivors and those without native liver survival in terms of sex, initial tumor size, initial AFP levels, maximum tumor size after neoadjuvant chemotherapy, or PRETEXT stage." (PMID 28851352, 2017). "PC materials could also be used for multiple electrochemiluminescent immunoassays for tumor marker detection, which could be further developed for practical clinical detection of serum CEA and AFP levels." (PMID 28475387, 2017). "Serum tumor markers were increased; the patient’s protein induced by vitamin K absence or antagonist-II (PIVKA-II) level was 2737 mAU/ml, and his alpha-fetoprotein (AFP) level was 23,054 ng/ml." (PMID 29198012, 2017). "The tumor cells stained positive for AFP and Sal-like protein 4 (SALL4), but were negative for carcinoembryonic antigen, synaptophysin, chromogranin A, and neural cell adhesion molecule." (PMID 28545511, 2017). "Log‐rank tests also revealed that K19 expression, serum CYFRA 21‐1 (≥2.7 ng/mL), high preoperative alpha‐fetoprotein (AFP) level (>20 ng/mL), tumor size (≥5 cm), the presence of multiple tumors, poor tumor differentiation, and microvascular invasion were associated with reduced OS rates." (PMID 28965351, 2017). "Our tissue microarray data showed that high expression of FOXP3 in tumor tissue significantly correlated with low serum AFP level, absence of vascular invasion and early TNM stage, suggesting a negative regulatory role of FOXP3 in HCC progression." (PMID 28903735, 2017). "Serum cfDNA levels are significantly higher in HCC patients than in control subjects and are associated with tumor size and differentiation but not age, gender, TNM stage or the levels of AFP or des-γ-carboxy prothrombin (DCP)." (PMID 27590520, 2016). "However, treatment of cancer-bearing rats with 1,3-BPMU significantly decreased the level of AFP and CEA as compared to tumor rats." (PMID 27187346, 2016). "In practice, if the AFP is negative (<20 IU/ml) but MDK elevated (≥0.44 ng/ml), a higher index of suspicion for an AFP-negative tumour is warranted." (PMID 27219517, 2016). "However, only age, tumor size, pathological type, tumor depth, LNM, CA19-9, and AFP were independent prognostic factors according to multivariate analysis." (PMID 27533455, 2016). "Similarly, the significant factors for OS for those with HCC were gender, AFP, ALT, TNM stage, tumor number, PVTT, tumor differentiation, resection margin, intraoperative blood loss, NLR, PLR, PNI and APRI (all P < 0.05)." (PMID 26907597, 2016). "Other tumor markers, such as AFP, LDH, CEA, and b-HCG, when measured, are negative, being substantial for the exclusion of malignancy." (PMID 28003830, 2016). "Similar results were also observed in patients with normal serum AFP level (< 20 μg/L), poor tumor differentiation (Edmondson grade III + IV), and absence of hepatocirrhosis." (PMID 27661119, 2016). "Increased FDG uptake within HCC nodules was associated with larger and less differentiated tumours, whereas ADC values observed in this study population appear not to correlate with AFP, differentiation on pathology and Milan criteria." (PMID 26883745, 2016).
tumor (continued). "Serum CA19-9 levels were correlated with gender, age, and tumor depth (all P<0.05), serum AFP levels were correlated with pathological type (P=0.005), and serum CA125 levels were correlated with gender, tumor size, pathological type, tumor depth, and LNM (all P<0.05)." (PMID 27533455, 2016). "(a: MAGL IOD values, p = 0.010; b: AFP values, p < 0.001; c: tumor sizes, p < 0.001; d: tumor numbers, p = 0.038; e: tumor embolus or not, yes: 2, no: 1, p < 0.001)." (PMID 27767105, 2016). "Other tumor markers, including CEA, AFP, lactate dehydrogenase, and beta-human chorionic gonadotropin, may be elevated but are more commonly associated with malignant and immature tumors." (PMID 27660731, 2016). "The only organs that remain a diagnostic challenge for 18FDG-PET/CT are the colon, breast, stomach, urinary tract and the carcinomas for which there are specific tumour markers [prostate-specific antigen (PSA), alpha fetoprotein (AFP), calcitonin, chromogranin A]." (PMID 26749430, 2016). "A parametric multivariable survival model was then used to calculate the relative prognostic value of ITA.LI.CA tumor stage, Eastern Cooperative Oncology Group (ECOG) performance status, Child–Pugh score (CPS), and alpha-fetoprotein (AFP) in predicting individual survival." (PMID 27116206, 2016). "Among separate groups, absent AE (p = 0.008), lower AFP (p = 0.014), tumor numbers ≤ 3 (p = 0.032), and sorafenib duration ≤ 1 cycle (p = 0.003) presented significant difference affecting patient’s survival." (PMID 27117280, 2016). "When we examined the cytotoxicity of the AFP-specific CTLs in in vivo mouse models, we found that AFP-specific CTLs expanded by DC and BA15 displayed significant tumor suppressive functions when compared with unspecific activated CTLs and control group treated with PBS." (PMID 27007051, 2016). "The ITA.LI.CA prognostic system includes both a tumor staging—stratifying patients with HCC into six main stages (0, A, B1, B2, B3, and C)—and a prognostic score—integrating ITA.LI.CA tumor staging, CPS, ECOG performance status, and AFP." (PMID 27116206, 2016). "The RT group had significantly better PS than the non-RT group; however, the RT group exhibited significantly worse prognostic factors than the non-RT group, including larger tumor size, higher AFP levels, and greater PV invasion." (PMID 27486881, 2016). "The PHC patients were sub-grouped by serum AFP level, BCLC stage, tumor size and histological type." (PMID 27590520, 2016). "Combination of simultaneous elevation of tumor makers (AFP and CA19-9) and tumor mark elevation (AFP or CA19-9) in discordance with presumptive imaging findings on CEUS or CT may lead significantly more patients to be suspicious of the diagnosis of cHCC-CC." (PMID 26917546, 2016). "AFP and PIVKA-II have been suggested as a tumor marker for the disease." (PMID 27488314, 2016). "The results showed that the tumor cells were strongly and diffusely positive for AFP, whereas the adjacent non-neoplastic hepatocytes and bile ducts were completely negative." (PMID 27301956, 2016). "AFP may be a useful tumor marker in poorly differentiated CRC with neuroendocrine component patients, for early detection of tumor recurrence." (PMID 26976278, 2016). "Furthermore, high FAM83D expression was verified correlating with tumor size, tumor number, PVTT and AFP levels." (PMID 27769048, 2016). "Although conventional clinicopathological characteristics, such as the alpha fetoprotein (AFP), hepatitis virus infection, tumor stage, histological grade, tumor size, microvascular invasion are generally regarded as prognostic factors for HCC patients, biomarkers are needed in clinical practice." (PMID 27835881, 2016). "Additionally, the positive rates of DCP were higher than those of AFP in HCC with different tumor sizes, and in cohort A, the total positive rate of DCP in HCC was 82.6%, which was remarkably higher than that of AFP (67.8%)." (PMID 27070780, 2016).